BRAF (B-Raf proto-oncogene, serine/threonine kinase)
Diseases named in the same sentence as BRAF in open-access papers (continued):
Sharing a sentence is not in itself a finding about the gene and the disease.
melanoma (continued). "Among the five melanomas harboring a rare BRAF mutation, two samples with the BRAF p.Asp594Asn showed an additional mutation in the NRAS (p.Gly12Asp) or in the KRAS (p.Gln61His) gene, previously identified in routine analysis." (PMID 31547467, 2019). "The majority of melanoma patients harboring BRAF and NRAS mutations exhibited the well-known hotspot driver mutations at the V600 (42/44 samples) and Q61 (10/10 samples) loci, respectively." (PMID 30820351, 2019). "In parallel to the imaging scans, the patient was monitored for melanoma and colorectal cancer by tracking BRAF p.V600R and KRAS p.G13D mutations in ctDNA respectively." (PMID 31727009, 2019). "To gain insight into the molecular pathogenesis of mucosal melanoma, we compiled BRAF mutations in 1312 mucosal melanoma from 33 publications and added the data from 27 mucosal melanomas from our own research center." (PMID 31398831, 2019). "V600E is the most abundant mutation in BRAF; therefore, BRAF V600E is the most popular target of melanoma treatment." (PMID 31307243, 2019). "In our study we used ddPCR to investigate the clinical validity of ctDNA measurements in melanoma patients treated with bevacizumab monotherapy by quantifying BRAF, NRAS and TERT promoter mutations in plasma." (PMID 31767937, 2019). "An open-label phase III trial investigated the efficacy of 18 dabrafenib and trametinib combination treatment in 704 patients with BRAF-mutated metastatic 19 melanoma." (PMID 31803366, 2019). "Based on these findings, phase I/II clinical studies using the HDAC inhibitor vorinostat in resistant BRAF V600-mutated advanced melanoma have been performed in the Netherlands." (PMID 31514399, 2019). "In melanoma, targeted therapies are optimized for patients bearing activating mutations in the BRAF and KIT oncogenes." (PMID 31547467, 2019). "In particular, the discoveries of BRAF mutations and their functions in most melanomas have led to the development of molecular therapy targeting the mutant BRAF1." (PMID 31239444, 2019). "The goal of this retrospective study was to validate the previously developed BDX008 test in melanoma patients treated with anti-PD-1 therapy and to evaluate its role depending on BRAF mutation status." (PMID 30925943, 2019). "The mutations of KRAS and BRAF oncogenes are involved in colorectal cancer and melanoma, while the NRAS mutations are associated with melanoma." (PMID 30935124, 2019). "39,40 A similar tiered approach can be utilized in the early detection of melanoma harboring BRAF-V600E mutations." (PMID 30701196, 2019). "With the advent of newer and more sensitive detection methods, a low incidence of a mutation (e.g., a partially BRAF V600E-mutated malignant melanoma) can be diagnosed." (PMID 30357519, 2019). "Advanced melanoma treatments often rely on immunotherapy or targeting mutations, with few treatment options for wild-type BRAF (BRAF-wt) melanoma." (PMID 30428063, 2019). "For example, patient MM475 had multiple recognized melanoma driver mutations including BRAF p.V600R, RAC1 p.P29S, MAP2K1 p.P124S, TERT C228T, and DPH3 C8T." (PMID 30312528, 2019). "Gain-of-function BRAF mutations have been identified in 7% of other human cancers, such as colorectal cancer, melanoma, papillary thyroid carcinoma, and some lymphomas." (PMID 31139472, 2019). "Treatment with BRAF inhibitors is effective in approximately 50% of melanoma patients bearing the BRAFV600E mutation, providing a significant survival benefit, even if acquired resistance can occur." (PMID 31083627, 2019). "As BRAF inhibitor PLX4032 induced resistance in melanoma patients bearing BRAFV 600E mutation, we also determined the efficacy of CUMA on A375-R, an in-house established BRAFV 600E mutant melanoma cell line with acquired resistance to PLX4032." (PMID 30745871, 2019).
melanoma (continued). "The development of inhibitors targeting mutated BRAF (found in around 60% of melanoma patients) has markedly improved overall survival of patients with late-stage tumors, even more so when combined with MEK inhibitors targeting the same signaling pathway." (PMID 30728057, 2019). "Unfortunately, results of the basket clinical trial of vemurafenib for non-melanoma tumors with the BRAF-V600E mutation indicated that other cancers, including colorectal, lung, and ovarian responded poorly to vemurafenib monotherapy." (PMID 31672130, 2019). "Metastatic melanoma was confirmed histologically, and further testing confirmed a BRAF V600R mutation via Sanger sequencing." (PMID 31727009, 2019). "In the present study, we have shown for the first time that the development of acquired resistance to BRAFi causes a significant increase in IL‐6 secretion in BRAF‐mutant melanoma cells." (PMID 30582770, 2019). "The discovery that most malignant melanomas bear an activating mutation of BRAF lead to the development of BRAF inhibitors." (PMID 31762942, 2019). "Univariate e multivariate analysis of factors associated to progression-free survival (PFS) in BRAF mutated melanoma patients treated with dabrafenib and trametinib." (PMID 30939167, 2019). "Especially elder patients with head and neck melanomas are prone to express BRAF V600K –mutation in their melanomas." (PMID 31039200, 2019). "They show that in BRAF-mutated melanoma patients after 3 days of treatment with BRAF and MEK inhibitors there is a statistically significant increase in the number of CTCs bearing activated pErbB3 receptor as compared to CTCs before initiation of treatment." (PMID 31557826, 2019). "The BRAF V600E mutation is present in approximately 60% of melanoma, 40% of non-small cell lung cancer (NSLCL), and 12% of colorectal cancer." (PMID 31466300, 2019). "The identification of disease driver genes in some solid tumors holds promise for precision medicine, such as ALK inhibitors in non-small cell lung cancer with an ALK rearrangement or BRAF inhibitors in melanoma with a BRAF mutation." (PMID 31395065, 2019). "In contrast, BRAF mutations are more commonly seen in acquired nevi, a characteristic they have in common with many melanomas." (PMID 31861163, 2019). "Further prospective studies are warranted to elucidate the clinical outcomes and benefits of newly developed targeted therapy in melanoma patients carrying each class of BRAF mutation." (PMID 31277584, 2019). "The comparison shows that not only are BRAF mutations less frequent in mucosal melanoma, but there is also a noticeable difference regarding the location of BRAF mutations between both melanoma subtypes." (PMID 31398831, 2019). "BRAF V600E mutation has been established in various types of cancers, like melanoma, papillary thyroid carcinoma, and metastatic colorectal adenocarcinoma with a frequency of mutation at about 50%, 45%, and 9%, respectively." (PMID 31781475, 2019). "BRAF gene mutations are found in 52% of melanomas, and 90% of those mutations are a single nucleotide alteration (nucleotide 1799 T>A), resulting in substitution of glutamic acid for valine (BRAFV600E)." (PMID 30499222, 2019). "Concomitant mutations in these genes along with BRAF in melanoma and other cancers provide evidence for this mechanism." (PMID 31527903, 2019). "The BRAF V600E mutation, which was indeed one of the first mutations discovered in melanoma has led to the discovery of specific BRAF inhibitor vemurafenib." (PMID 30987166, 2019). "We performed a retrospective analysis of plasma ctDNA using droplet digital PCR (ddPCR) in 30 primary melanoma patients with tumors harboring BRAF, NRAS or TERT promoter mutations." (PMID 30719207, 2019). "We show that BI-78D3 has antitumor activity in BRAF/MEK inhibitor-naïve and BRAF/MEK inhibitor-resistant melanoma cells containing a BRAF mutation, demonstrating its obvious potential to overcome acquired resistance to BRAF and MEK inhibitors." (PMID 31745079, 2019).
melanoma (continued). "This oncosuppressor miRNA controls the expression of two oncoproteins BRAF and MDM2, is strongly downregulated in BRAF-mutated melanomas and is able to impair the development of resistance to MAPK inhibitors." (PMID 30254376, 2019). "Activating PIK3CA mutations affecting codons 542, 545 or 1047 were observed in 2 melanomas with a class-1 BRAF mutation and 1 melanoma with a class-3 BRAF mutation." (PMID 31277584, 2019). "The acidosis in TME was reported to promote the constant phosphorylation of AKT in BRAF-mutated melanoma cells, which activates mTOR signaling and confers vemurafenib resistance." (PMID 30927928, 2019). "The discovery that oncogenic activating mutations in BRAF occur in malignant melanoma paved the way for the development of a number of specific inhibitors targeting mutant BRAF, including the small-molecule inhibitor vemurafenib." (PMID 31416288, 2019). "We demonstrated coexisting mutations of these driver genes in melanomas, and categorize BRAF mutations based on the new classification system to elucidate their association with clinical characteristics." (PMID 31277584, 2019). "In this study, firstly we applied WGCNA to identify the two key modules in melanoma that were associated with the expression of BRAF gene (the brown module was positive, and the turquoise was negative)." (PMID 30925905, 2019). "al. studied IHC scoring in challenging cases of malignant melanoma, which required the assessment pf the BRAF V600E mutation for target therapy." (PMID 31531096, 2019). "Here, we report that in response to proinflammatory cytokines, BRAF is subjected to lysine 27-linked poly-ubiquitination in melanoma cells by the ITCH ubiquitin E3 ligase." (PMID 31015455, 2019). "Somatic missense mutations in BRAF have been found in approximately 10% and 60% of colorectal tumors and melanoma lesions, respectively." (PMID 31635038, 2019). "BRAF mutations are common in various human cancers; the point mutation V600E accounts for 80% of all BRAF mutations, especially in melanoma." (PMID 31108873, 2019). "Most of the melanoma patients with the BRAF mutation carry the BRAF V600E mutation, and these patients can be treated with BRAF-targeted therapy (e.g., vemurafenib, dabrafenib) in combination with MEK inhibitors (e.g., trametinib, cobimetinib)." (PMID 31623406, 2019). "For example, inhibition of mitochondrial biogenesis with gamitrinib, a mitochondrial HSP90 inhibitor, effectively eradicated BRAF-mutated melanoma cells, which were resistant to a MAPK inhibitor." (PMID 30771209, 2019). "BRAF mutations have a very high frequency in hairy cell leukemia (80–100%), melanoma (30–70%), papillary thyroid tumors (36–83%), type I ovarian (30%) and colorectal cancer (10%)." (PMID 31540406, 2019). "A number of small molecules have been introduced by far to inhibit BRAF, some of which are approved by the FDA for targeting BRAF mutated malignant melanoma." (PMID 31370278, 2019). "In a panel of 49 melanoma-derived cell lines, we sequenced oncogenes that are commonly mutated in melanoma (BRAF, NRAS, KRAS)." (PMID 31253656, 2019). "FGFs were found among senescence-associated factors expressed and released by melanoma cells in response to BRAF and MEK inhibition." (PMID 31167513, 2019). "In a randomized phase 3 trial, it extended median overall survival (OS) for patients by four months compared to chemotherapy in BRAF-mutated advanced melanoma patients." (PMID 31231466, 2019). "The BRAF oncogene has recently been implicated in cellular metabolism in melanoma, specifically in mediating resistance to energetic stress." (PMID 30651927, 2018). "The BRAF oncoprotein, discovered in 1988, is associated with nearly 66% of melanomas and 12% of colorectal cancers." (PMID 29565994, 2018). "Each activating variant was introduced into the BRAFV600E-mutant and BRAF inhibitor-sensitive human melanoma cell lines, MM200 and SKMel28." (PMID 30237495, 2018).
melanoma (continued). "The discovery of the frequent BRAF(V600E) mutation in human melanoma tumors offered the first opportunity to develop an oncogene-directed therapy for these patients profiting the use of selective inhibitors of constitutive BRAF activity." (PMID 30191142, 2018). "Across all cancer types, the BRAF V600E mutation occurs in 8% of cancers, with melanoma having the highest rate of BRAF V600E mutations at 66%, followed by papillary thyroid cancer (53%) and serous ovarian cancer (30%)." (PMID 30598662, 2018). "Previous studies have revealed that more than 60% of malignant melanoma patients carry mutations in the BRAF gene, and all mutations are localized within the kinase domain." (PMID 30463359, 2018). "A BRAF oral inhibitor, vemurafenib, is effective in the treatment of advanced stages of melanoma with the V600E mutation." (PMID 29973561, 2018). "Oncogenic BRAF activation is implicated in approximately 50% of melanomas and between 8 and 10% of colon cancers." (PMID 29844307, 2018). "Combination therapy with BRAF and MEK inhibitors significantly improves survival in BRAF mutated melanoma patients but is unable to prevent disease recurrence due to the emergence of drug resistance." (PMID 30558661, 2018). "BRAFi combination therapies showed a response rate of 50% in BRAF V600E-mutated non-melanoma tumors." (PMID 30220966, 2018). "Since nearly 50% of BRAF mutations have the V600E mutation, vemurafenib is a crucial anti-melanoma and anti-metastatic drug due to its specific inhibition of BRAFV600E." (PMID 29565994, 2018). "In one study of 318 melanoma specimens, mutations in BRAF or NRAS were detected in 166 (52%) and 88 (28%), respectively." (PMID 30113761, 2018). "Cohorts B and C comprised patients with BRAF‐ or NRAS‐mutant melanoma who had either undergone surgical resection of high‐risk disease (cohort B) or were receiving or had received medical therapy for advanced disease (cohort C)." (PMID 30113761, 2018). "BRAF mutations have been detected in 7% of all cancers and 66% of melanomas; as such, the FDA has approved a few BRAF inhibitor drugs to date." (PMID 29565994, 2018). "The adjuvant treatment landscape in high-risk resected melanoma is actively evolving, with increasing emphasis on immune checkpoint inhibition as well as BRAF targeted therapy." (PMID 29773080, 2018). "Human melanoma SK-MEL-28 cells with BRAF mutation are known to be sensitive to trametinib; however, the level of phosphorylated Akt was clearly elevated after trametinib treatment." (PMID 29731968, 2018). "This BRAF mutation is found in approximately 50% of patients with advanced melanoma and causes constitutive activation of the Mitogen Activated Protein Kinase (MAPK) pathway." (PMID 29315345, 2018). "Three melanoma cell lines harbouring an activating mutation in BRAF were treated continuously with PLX4720 (a BRAF inhibitor) to develop drug resistance." (PMID 29662054, 2018). "Nonetheless, univariate analysis clearly illustrated the prognostic value of ICAM-1 for MSS in NRAS/BRAF melanoma, where reduced expression is associated with worst survival, a finding that has not been widely reported in melanoma." (PMID 30116025, 2018). "In BRAF-mutated melanoma, a phase II study of dabrafenib and trametinib for patients with brain metastases demonstrated intracranial response rates of 44–59% in cohorts stratified by BRAF mutation type, prior CNS therapy, symptoms, and performance status." (PMID 30356657, 2018). "In clinical practice, it is now routine to screen for BRAF V600 mutations in metastatic melanoma patients since there are approved targeted therapies to treat advanced melanoma patients." (PMID 30116025, 2018). "Somatic mutations of BRAF are found with particularly high frequency in melanoma and colorectal, ovarian, and thyroid carcinomas." (PMID 29434027, 2018). "Only a subpopulation of melanomas harbors the crucial oncogenic BRAF-mutation, and even in mutated melanomas a therapy resistance rapidly develops." (PMID 29454361, 2018).
melanoma (continued). "Activating BRAF mutations at codon 600 (mainly V600E) are found in approximately 50% of melanomas, particularly, in nodular and SSMs." (PMID 29946532, 2018). "Experiments were then performed to investigate the ability of δ-TT to affect the A375 stem cell subpopulation and to compare it with that of vemurafenib, the classical targeted therapeutic compound utilized for the treatment of BRAF mutated melanomas." (PMID 29330434, 2018). "The identification of BRAF V600 somatic mutations in melanoma led to the development of molecularly targeted therapies, which improved the prognosis of metastatic melanoma patients compared to chemotherapy." (PMID 29552321, 2018). "Melanoma evolution after anti-PD-1 initiation was analyzed in BRAF-mutated and BRAF wild-type patients." (PMID 29970025, 2018). "One example of this approach has been reported in the case of secondary mutations in the MEK–ERK pathway in vemurafenib-resistant BRAF-mutant melanomas." (PMID 30487290, 2018). "Historically, anti-PD-1 therapy was approved after ipilimumab failure in BRAF wild-type metastatic melanoma and BRAFi failure in BRAF-mutated melanoma." (PMID 29970025, 2018). "Of patients with brain metastases from melanoma, 40–50% harbor BRAF mutations, and the use of the BRAF inhibitor vemurafenib is associated with 18–20% response rates and dabrafenib yields 30–40% response rates." (PMID 30473769, 2018). "Prior meta-analyses in lung cancer have shown decreased response to ICI in EGFR or ALK mutant subgroups, while BRAF mutations in melanoma have shown the opposite effect." (PMID 29743104, 2018). "Taken together, E2F1 loss enhances sensitivity of melanoma cells to targeted therapies and induces the death of BRAF inhibitor-resistant melanoma cells." (PMID 29743521, 2018). "The BRAF V600E mutation, resulting in a single valine-to-glutamate substitution, accounts for the majority of the BRAF mutations among melanoma patients." (PMID 30463359, 2018). "BRAF kinase inhibitors (BRAFi) like vemurafenib (Vem; marketed as Zelboraf) and dabrafenib (Dabra) have become the standard targeted therapy for melanoma patients with BRAF mutations." (PMID 29346301, 2018). "Dabrafenib is a BRAF inhibitor that was approved by National Institute of Clinical Excellance (NICE) in United Kingdom (UK) for treating unresectable or metastatic BRAF V600 mutation-positive melanoma in 2014." (PMID 30255823, 2018). "The choice of melanoma derives from our recent study, which indicates that NAMPT becomes the dominant NAD-biosynthetic enzyme in BRAF-resistant melanoma cell lines and patients BRAF-mutated." (PMID 29721178, 2018). "Overexpression of mutated BRAF into immortalized melanocytes induces anchorage-independent growth, mediates melanoma cell invasion and the development of tumors in mice." (PMID 29455659, 2018). "According to the TCGA data analysis, TERT promoter mutations frequently occur in melanoma, mainly in the BRAF (75% of cases), RAS (72% of cases), and NF1 (83% of cases) subtypes, suggesting a link between MAPK activation and TERT expression." (PMID 30166456, 2018). "Survival differences according to BRAF mutation status reported for patient cohorts after resection of primary melanomas have been inconsistent." (PMID 30010756, 2018). "Vemurafenib (PLX4032), a specific BRAF inhibitor (BRAFi), has been approved to treat late-stage melanoma with BRAFV600E mutation." (PMID 30100999, 2018). "VE1 immunostaining for the detection of BRAF-mutated protein is a quick and inexpensive test that can be combined with other melanoma markers." (PMID 29148538, 2018). "Nevertheless, in defined genetic contexts, such as in vivo melanoma models where BRAF is mutated, PTEN is usually deleted and β-catenin is then stabilized, leading to an increase in metastatic events." (PMID 30166456, 2018).